FBXW12 (F-box and WD repeat domain containing 12)
Description:
Substrate-recognition component of the SCF (SKP1-CUL1-F-box protein)-type E3 ubiquitin ligase complex. Promotes degradation of interleukin-22 receptor subunit IL22RA1 in resting and IL22-stimulated conditions by facilitating its ubiquitination. Functions as a cell growth suppressor.
Synonyms: FBW12; FBXO12; FBXO35
Tractability: PROTAC: ubiquitination databases record sites on it.
Gene: Protein-coding gene on chromosome 3 (48,372,219 to 48,401,259, forward strand). Ensembl gene ENSG00000164049.
Subcellular location (Human Protein Atlas): Cytosol; Vesicles
Pathways (Reactome):
Immune System: Antigen processing: Ubiquitination & Proteasome degradation
Metabolism of proteins: Neddylation
Gene Ontology:
Biological process: SCF-dependent proteasomal ubiquitin-dependent protein catabolic process; protein ubiquitination
Cellular component: cytosol; SCF ubiquitin ligase complex; cytoplasm
Genetic constraint (gnomAD): Loss-of-function variants: 39 observed, 48.96 expected, observed/expected ratio (o/e) 0.8, 90% interval 0.62 to 1.04. The upper end of that interval is the gene's LOEUF score, 1.04, which puts it in group 4 of 6, group 1 being the genes least tolerant of losing a copy. Missense variants: 446 observed, 503.97 expected, observed/expected ratio (o/e) 0.88, 90% interval 0.82 to 0.96. Synonymous variants: 160 observed, 187.12 expected, observed/expected ratio (o/e) 0.86, 90% interval 0.75 to 0.98.
Homologues: Orthologues: chimpanzee FBXW12 (99% identical), macaque FBXW12 (80% identical), dog FBXW12 (58% identical), rabbit FBXW12 (51% identical), rat Fbxw12 (42% identical), mouse Fbxw20 (42% identical), mouse Fbxw25 (42% identical), mouse Fbxw22 (42% identical), mouse Fbxw13 (41% identical), mouse Fbxw26 (41% identical), mouse Fbxw18 (41% identical), mouse Fbxw24 (41% identical), and 15 more. Paralogues in human: FBXW7 (12% identical), WDR49 (12% identical), EFCAB8 (11% identical), BTRC (11% identical), FBXW9 (11% identical), FBXW11 (10% identical), WDR86 (10% identical), WDR64 (10% identical), TRAF7 (10% identical), FBXW8 (8% identical), PAAF1 (8% identical), FBXO16 (6% identical), and 2 more.
Diseases named in the same sentence as FBXW12 in open-access papers:
FBXW12 is named in the same sentence as 4 diseases in open-access papers, as found by Europe PMC text mining. Sharing a sentence is not in itself a finding about the gene and the disease. The quoted sentences say what the papers report.
Alzheimer disease (1 paper, 2020). A progressive, neurodegenerative disease characterized by loss of function and death of nerve cells in several areas of the brain leading to loss of cognitive function such as memory and language. "Interestingly, alterations in both ASB9 and FBXW12 have also been associated with Alzheimer's disease (40, –, 42)." (PMID 31911436, 2020).
cancer (3 papers, 2022 to 2024). A tumor composed of atypical neoplastic, often pleomorphic cells that invade other tissues. "we further investigated that FBXW5 was highly expressed, FBXW10 and FBXW12 were lowly expressed, and other members were moderately expressed in pan-cancer." (PMID 36591289, 2022).
neoplasia (1 paper, 2015). "However, there is a theoretical hazard in FBXW12 antagonism, as unchecked cytoproliferation may drive neoplasia and some authors implicate IL-22 signaling in inflammatory disease." (PMID 26171402, 2015).
FBXW12 also shares sentences with these, for which no sentence is quoted: infection (1 paper).